DDX17 (DEAD-box helicase 17)
Description:
As an RNA helicase, unwinds RNA and alters RNA structures through ATP binding and hydrolysis. Involved in multiple cellular processes, including pre-mRNA splicing, alternative splicing, ribosomal RNA processing and miRNA processing, as well as transcription regulation. Regulates the alternative splicing of exons exhibiting specific features. For instance, promotes the inclusion of AC-rich alternative exons in CD44 transcripts. This function requires the RNA helicase activity. Affects NFAT5 and histone macro-H2A.1/MACROH2A1 alternative splicing in a CDK9-dependent manner. In NFAT5, promotes the introduction of alternative exon 4, which contains 2 stop codons and may target NFAT5 exon 4-containing transcripts to nonsense-mediated mRNA decay, leading to the down-regulation of NFAT5 protein. Affects splicing of mediators of steroid hormone signaling pathway, including kinases that phosphorylates ESR1, such as CDK2, MAPK1 and GSK3B, and transcriptional regulators, such as CREBBP, MED1, NCOR1 and NCOR2. By affecting GSK3B splicing, participates in ESR1 and AR stabilization. In myoblasts and epithelial cells, cooperates with HNRNPH1 to control the splicing of specific subsets of exons. In addition to binding mature mRNAs, also interacts with certain pri-microRNAs, including MIR663/miR-663a, MIR99B/miR-99b, and MIR6087/miR-6087. Binds pri-microRNAs on the 3' segment flanking the stem loop via the 5'- [ACG]CAUC[ACU]-3' consensus sequence. Required for the production of subsets of microRNAs, including MIR21 and MIR125B1. May be involved not only in microRNA primary transcript processing, but also stabilization (By similarity). Participates in MYC down-regulation at high cell density through the production of MYC-targeting microRNAs. Along with DDX5, may be involved in the processing of the 32S intermediate into the mature 28S ribosomal RNA. Promoter-specific transcription regulator, functioning as a coactivator or corepressor depending on the context of the promoter and the transcriptional complex in which it exists. Enhances NFAT5 transcriptional activity. Coactivates MMP7 transcription. Along with CTNNB1, coactivates MYC, JUN, FOSL1 and cyclin D1/CCND1 transcription. Alone or in combination with DDX5 and/or SRA1 non-coding RNA, plays a critical role in promoting the assembly of proteins required for the formation of the transcription initiation complex and chromatin remodeling leading to coactivation of MYOD1-dependent transcription. This helicase-independent activity is required for skeletal muscle cells to properly differentiate into myotubes. During epithelial-to-mesenchymal transition, coregulates SMAD-dependent transcriptional activity, directly controlling key effectors of differentiation, including miRNAs which in turn directly repress its expression. Plays a role in estrogen and testosterone signaling pathway at several levels. Mediates the use of alternative promoters in estrogen-responsive genes and regulates transcription and splicing of a large number of steroid hormone target genes. Contrary to splicing regulation activity, transcriptional coregulation of the estrogen receptor ESR1 is helicase-independent. Plays a role in innate immunity. Specifically restricts bunyavirus infection, including Rift Valley fever virus (RVFV) or La Crosse virus (LACV), but not vesicular stomatitis virus (VSV), in an interferon- and DROSHA-independent manner. Binds to RVFV RNA, likely via structured viral RNA elements. Promotes mRNA degradation mediated by the antiviral zinc-finger protein ZC3HAV1, in an ATPase-dependent manner.
Synonyms: P72; RH70
Tractability: Small molecule: a structure with a bound ligand is known. PROTAC: UniProt records ubiquitination sites on it; ubiquitination databases record sites on it; its protein half-life has been measured.
Target class: Enzyme; Hydrolase
Gene: Protein-coding gene on chromosome 22 (38,483,438 to 38,507,660, reverse strand). Ensembl gene ENSG00000100201.
Subcellular location: Nucleus; Nucleus, nucleolus; Cytoplasm, cytosol
Subcellular location (Human Protein Atlas): Nuclear speckles
Pathways (Reactome):
Metabolism of proteins: SUMOylation of transcription cofactors
Gene Ontology:
Molecular function: ATP hydrolysis activity; protein binding; RNA binding; transcription coactivator activity; ATP-dependent activity, acting on RNA; RNA helicase activity; ATP binding; chromatin DNA binding; lncRNA binding; nucleic acid binding
Biological process: alternative mRNA splicing, via spliceosome; androgen receptor signaling pathway; epithelial to mesenchymal transition; estrogen receptor signaling pathway; miRNA metabolic process; positive regulation of transcription by RNA polymerase II; regulation of alternative mRNA splicing, via spliceosome; regulation of skeletal muscle cell differentiation; regulation of transcription by RNA polymerase II; myoblast differentiation; RNA processing; gene expression; miRNA transcription
Cellular component: membrane; nuclear speck; nucleus; nucleoplasm; ribonucleoprotein complex; cytosol; nucleolus
Genetic constraint (gnomAD): Loss-of-function variants: 10 observed, 67.33 expected, observed/expected ratio (o/e) 0.15, 90% interval 0.091 to 0.25. The upper end of that interval is the gene's LOEUF score, 0.25, which puts it in group 1 of 6, group 1 being the genes least tolerant of losing a copy. Missense variants: 584 observed, 953.24 expected, observed/expected ratio (o/e) 0.61, 90% interval 0.57 to 0.66. Synonymous variants: 334 observed, 333.86 expected, observed/expected ratio (o/e) 1, 90% interval 0.91 to 1.1.
Homologues: Orthologues: macaque DDX17 (99% identical), dog DDX17 (99% identical), guinea pig DDX17 (99% identical), chimpanzee DDX17 (96% identical), rabbit DDX17 (95% identical), rat Ddx17 (88% identical), mouse Ddx17 (88% identical), tropical clawed frog ddx17 (68% identical), zebrafish ddx17 (67% identical), Drosophila melanogaster CG10077 (48% identical), Caenorhabditis elegans ddx-17 (41% identical). Paralogues in human: DDX5 (58% identical), DDX42 (32% identical), DDX3X (30% identical), DDX3Y (29% identical), DDX43 (29% identical), DDX53 (28% identical), DDX46 (27% identical), DDX4 (26% identical), DDX41 (26% identical), DDX23 (23% identical), DDX21 (22% identical), DDX59 (21% identical), and 26 more.
Diseases named in the same sentence as DDX17 in open-access papers:
DDX17 is named in the same sentence as 81 diseases in open-access papers, as found by Europe PMC text mining. Sharing a sentence is not in itself a finding about the gene and the disease. The quoted sentences say what the papers report.
viral infection (20 papers, 2017 to 2026). "Given the fact that the uremia-associated immune deficiency is a well-known complication of CKD and it increase the risk of virus-infection and virus-associated cancers, the low DDX17 level in PBMC might associated with CKD progression." (PMID 36875100, 2023). "In some viral infections, DDX17 facilitates viral replication by interacting with viral and host proteins, enhancing the stability and packaging efficiency of viral RNA." (PMID 41367298, 2026). "Recent studies have highlighted DDX17’s multifaceted roles as a host factor in viral replication, revealing its dual function across various viral infections." (PMID 41367298, 2026). "The dual roles of DDX17 across different viral infections are closely related to its unique structural functions." (PMID 41367298, 2026). "Given DDX17’s pivotal role in various viral infections, it holds significant potential as a target for antiviral therapy." (PMID 41367298, 2026). "In particular, further exploration is needed to clarify the dynamic functions of DDX17 under diverse viral infection conditions and integrate these findings into a comprehensive mechanistic framework." (PMID 41367298, 2026). "DDX17 influences viral infections by modulating viral RNA synthesis and interacting with the host’s antiviral defenses." (PMID 41367298, 2026). "This review will explore the “love-hate” relationship of DDX17 with various viral infections, summarizing its roles and mechanisms." (PMID 41367298, 2026). "With advancements in molecular biology, researchers have gained a deeper understanding of the multifaceted roles of DDX17 in viral infections." (PMID 41367298, 2026). "DDX17 has a dual influence on viral infection: on one hand, it promotes the replication of certain viruses (e.g. HIV, influenza virus, and Hantaan virus) through interactions with viral proteins or RNA." (PMID 41367298, 2026). "This review systematically summarizes and analyzes the diverse functions and specific mechanisms of DDX17 during viral infections." (PMID 41367298, 2026). "Second, the dual roles of DDX17 in viral infections – facilitating or suppressing replication – suggest a need to investigate strategies for selectively modulating its activity or expression to target specific viral replication processes." (PMID 41367298, 2026). "The intricate interactions between DDX17 and various viruses provide a fresh perspective on the mechanisms of viral infections and lay a theoretical foundation for developing innovative antiviral strategies." (PMID 41367298, 2026). "DDX5 and DDX17 promote virus infection by enhancing viral gene expression via recruitment of host protein Brg1, a chromatin remodeler." (PMID 40257982, 2025). "This demonstrates a conserved function of gammaherpesviral protein kinases to interact with DDX5 and DDX17 and utilize these host proteins for viral infection." (PMID 40257982, 2025). "In response to viral infection, DDX17 translocates from the nucleus to the cytoplasm where the vRNAs are located." (PMID 28054965, 2017). "DDX17 exhibits dual functionality in viral infections: it enhances the stability, packaging, and replication of viral RNA through interactions with viral ribonucleoprotein complexes, as evidenced in infections caused by influenza viruses and Hantaan virus (HTNV)." (PMID 41367298, 2026). "Conversely, DDX17 exhibits an inhibitory effect in certain other viral infections." (PMID 41367298, 2026). "A growing body of evidence suggests that DDX5 and DDX17 play crucial roles during viral infection." (PMID 38553727, 2024). "We proceeded to investigate whether DDX17 acts in synergy or competition with DDX5 by analysing the impact of DDX17 knockdown in DDX5 KO HCT116 cells where viral infection is already weakened." (PMID 38553727, 2024). "However, upon viral infection, DDX17 is repurposed and exported to the cytoplasm, where it binds a stem-loop miRNA-like structure in RVFV RNA in order to restrict viral replication." (PMID 28054965, 2017).
viral infection (continued). "Additionally, DDX17 plays important roles in other viral infections." (PMID 41367298, 2026). "DDX17 (DEAD-box RNA helicase 17) is an essential RNA helicase and regulatory ATPase in host cells, extensively involved in various cellular processes during viral infections, such as RNA splicing, transcriptional regulation, and post-transcriptional modification." (PMID 41367298, 2026). "In contrast, we demonstrated that the single depletion of DDX17 reduces SINV infection in HCT116 cells and its combined depletion with DDX5 in the KO background further decreases viral levels, suggesting a synergism between the two proteins in promoting viral infection." (PMID 38553727, 2024).
hepatocellular carcinoma (14 papers, 2019 to 2025). A malignant tumor that arises from hepatocytes. "Previous data showed that DDX17 could regulate alternative splicing and produce oncogenic molecules that promote hepatocellular carcinoma metastasis, indicating that DDX17 expression was strongly associated with patient outcomes." (PMID 38213773, 2024). "DDX17 can induce intron 3 retention of PXN-AS1 in hepatocellular carcinoma cells to produce PXN-AS1-IR3, which activates the MYC signaling pathway and promotes tumor progression by binding to Tex10." (PMID 41322492, 2025). "Chen’s group confirmed that DDX17 acts as a pro-tumor splicing factor during hepatocellular carcinoma (HCC) progression and identified it as an oncoprotein." (PMID 40526173, 2025). "DDX17 also acts as a co-regulator of transcription factors such as estrogen receptor alpha (ERα) to promote hepatocellular carcinoma progression." (PMID 41322492, 2025). "Aberrant DDX17 expression has been found in hepatocellular carcinoma (HCC), colon cancer, glioma and lung cancer." (PMID 36164607, 2022). "RNA helicases also have known roles in cancer; in particular, DDX5 promotes GC cell proliferation, and DDX17 hepatocellular carcinoma progression via inhibiting Klf4 transcriptional activity." (PMID 35566209, 2022). "In hepatocellular carcinoma cells, DDX17 is overexpressed, and DDX17 induces intron 3 retention in PXN-AS1, promoting the generation of the PXN-AS1-IR3 transcript." (PMID 35992805, 2022). "DDX17 promotes the formation of hepatocellular carcinoma by inhibiting Klf4 transcriptional activity." (PMID 33000861, 2020). "In a variety of cancers, such as colon, breast, prostate, non-small cell lung, glioma, and hepatocellular carcinoma, DDX17 promotes cancer cell proliferation and inhibits apoptosis through the activation or inhibition of specific signaling pathways, thereby promoting tumorigenesis and progression." (PMID 41322492, 2025). "Emerging evidence has indicated that DDX17 acts as a transcriptional coregulator or a cofactor of microprocessors in cancer development, such as in non-small cell lung cancer, glioma cells, and hepatocellular carcinoma." (PMID 37720188, 2023). "For instance, DDX17 regulates breast cancer pathology by promoting the transcription of NFAT5 target genes, and facilitates hepatocellular carcinoma metastasis by regulating alternative splicing, leading to the production of oncogenic RNA subtypes." (PMID 37239217, 2023). "In hepatocellular carcinoma, ALDOA K230/K322 lactylation weakens its strong binding affinity with DEAD-box helicase 17, leading to their dissociation in the cytoplasm and promoting DEAD-box helicase 17 nuclear translocation and SOX2 upregulation, sustaining liver cancer stem cells properties." (PMID 40994548, 2025). "Thus, DDX17 can promote HCC cell migration and invasion, which lead to the progression of hepatocellular carcinoma." (PMID 35992805, 2022).
breast carcinoma (9 papers, 2013 to 2026). "Immunohistochemical analyses of 233 patients with ERα-positive breast cancers suggest that higher DDX17 expression is associated with better prognosis and is positively associated with HER2 negativity and progesterone receptor." (PMID 41322492, 2025). "For instance, DDX17 promotes EMT in breast cancer by modulating alternative splicing of CD44, thereby enhancing metastatic potential." (PMID 41367298, 2026). "and endoxifen and fulvestrant, which are endocrine therapy drugs, inhibit breast cancer by downregulating DDX5/DDX17 expression." (PMID 35992805, 2022). "The analyses revealed that the key components of microprocessor complex such as DGCR8, DDX5, and DDX17 are down-regulated in breast cancer as compared with the healthy samples." (PMID 34117091, 2021). "In breast cancer, sumoylation is overactivated and increases the stability of DDX5 and DDX17, which may explain the high DDX5/DDX17 expression in breast cancer." (PMID 35992805, 2022). "Although WBP2 did not regulate the expression level of the microprocessor complex components, that is, DGCR8, Drosha, DDX5, and DDX17, it suppressed the activity of pri-miRNA–processing machinery via physical interactions with these components in breast cancer." (PMID 34117091, 2021). "In breast cancer, DDX5/DDX17, auxiliary activators of ERα, are recruited to the ERα-responsive promoter to promote gene transcription." (PMID 35992805, 2022). "In line with previous findings, down-regulation of DDX5, DDX17, and DGCR8 transcript levels in breast cancer was observed." (PMID 34117091, 2021). "Next, we examined how the expression levels of DDX5, DDX17, and DGCR8 genes correlate with breast cancer patients’ survival." (PMID 34117091, 2021). "Silencing of DDX17 expression significantly inhibits the expression of estrogen-dependent genes (e.g., pS2, Cathepsin D) and the estrogen-dependent growth of MCF-7 and ZR75-1 breast cancer cells." (PMID 41322492, 2025). "Combined DDX5/DDX17/DGCR8 expression profiles as a signature showed a stronger effect, HR = 0.47 (95% CI: 0.4-0.55, logrank P-value = 1 × 1016), meaning that lower expression of this set of signature genes correlated with ∼2 times increase in the survival of breast cancer patients." (PMID 34117091, 2021).
colon cancer (8 papers, 2012 to 2025). "Mutations in KIAA1217, POLD1, PIEZO1, NBEAL2, DDX17, and PARP14 were significantly more prevalent in patients with colon cancer and PRShigh than in those with PRSlow." (PMID 38577604, 2024). "DDX17 is overexpressed in colon cancer, lung cancer, and glioma cancer, potentiating tumor cell proliferation and progression." (PMID 31653828, 2019). "p68 and the highly homologous protein p72 (Ddx17), are over-expressed and form complexes with β-Catenin in the nucleus of colon cancer cells to activate gene transcription and promote cell proliferation." (PMID 23349811, 2013). "A previous study revealed that DDX5, the homologous protein of DDX17, could directly interact with β-catenin to activate downstream gene transcription in colon cancer." (PMID 39897048, 2025). "Therefore, DDX5 or DDX17 is involved in the progression of various cancers (glioma, colon cancer, glioblastoma, colon adenocarcinoma, adult T-cell leukemia/lymphoma) by participating in the NF-κB signaling pathway." (PMID 35992805, 2022). "Similarly, high DDX17 expression leads to a worsened prognosis for patients with glioma, gastric cancer, pancreatic cancer, colon cancer, paclitaxel-resistant ovarian cancer, and other cancers." (PMID 35992805, 2022).